CXCR4 (C-X-C motif chemokine receptor 4)
Diseases named in the same sentence as CXCR4 in open-access papers (continued):
Sharing a sentence is not in itself a finding about the gene and the disease.
ovarian insufficiency (1 paper, 2012). "Studies from mouse models have shown that defects in PGC migration or proliferation (e.g. Steel, c-kit, Cxcr4) can be associated with subsequent ovarian germ cell depletion and ovarian insufficiency in postnatal or adult life." (PMID 22240064, 2012).
ovarian serous carcinoma (1 paper, 2022). "A tissue microarray of 47 primary high grade ovarian serous carcinomas and their recurrences was stained with primary antibodies directed against CXCR4 and pCXCR4." (PMID 35397601, 2022).
Paget’s disease of the breast (1 paper, 2022). "Increased expression and signalling of chemokines path ways, especially CXCR4, are observed in the lymphovascular invasion of Paget’s disease of the breast." (PMID 35685958, 2022).
paraganglioma (1 paper, 2017). A benign or malignant neoplasm arising from paraganglia located along the sympathetic or parasympathetic nerves. "In addition, the chemokine receptor CXCR4 and the endothelin receptor A (ETA) were evaluated for their suitability as novel diagnostic and therapeutic targets in paragangliomas." (PMID 29163802, 2017). "In our study, both CXCR4 and ETA were found to be intensely expressed on tumor vessels of the paragangliomas investigated." (PMID 29163802, 2017). "However, although many types of tumors have been studied for the expression of CXCR4, no respective investigations have been performed with (malignant) paragangliomas so far." (PMID 29163802, 2017).
parasitemia (1 paper, 2015). "Additionally, blocking the CXCR4/CXCL12 interaction causes an increase in circulating parasitemia, suggesting a pivotal role for CXCR4/CXCL12 signaling during malarial infection." (PMID 25909640, 2015).
pemphigoid (1 paper, 2020). "We detected higher expression of CXCR4 in OLPs than in other lesions (fibrous hyperplasia, cancer, pemphigoid and pemphigus)." (PMID 32214134, 2020).
placenta previa (1 paper, 2023). "This research was designed to probe the levels of the chemokine CXCL12 and the receptors CXCR4/CXCR7 in the placental tissues of patients with placenta previa and their effects on the biological functions of human trophoblast cells." (PMID 37589008, 2023). "Similarly, in our work, we found high CXCR4 and CXCR7 levels in the placental tissues of puerperae with placenta previa, and silencing of CXCR4 and CXCR7 led to diminished HTR8/SVneo cell proliferative, migratory, and invasive capabilities." (PMID 37589008, 2023). "CXCL12, CXCR4, and CXCR7 are highly expressed in placental tissues of patients with placenta previa and induce the biological activities of HTR8/SVneo cells." (PMID 37589008, 2023). "The relationship between the expression levels of CXCL12, CXCR4, and CXCR7 mRNA in placental tissues of the patients with placenta previa and their clinical parameters was analyzed." (PMID 37589008, 2023). "This research was designed to probe the expression of chemokine CXCL12 and its receptors CXCR4 and CXCR7 in placental tissues of patients with placenta previa and the effect of CXCL12/CXCR4/CXCR7 axis on the biological functions of human trophoblast cells." (PMID 37589008, 2023). "CXCL12, CXCR4, and CXCR7 expression in placental tissue from patients with placenta previa and healthy puerperae was detected." (PMID 37589008, 2023). "CXCL12, CXCR4, and CXCR7 expression was elevated in placental tissues from patients with placenta previa." (PMID 37589008, 2023). "The IHC results indicated that the expression of CXCL12, CXCR4, and CXCR7 in placenta tissues of patients with placenta previa was higher than those of normal puerperae." (PMID 37589008, 2023). "Additionally, the levels of CXCR4, CXCR7, and CXCL12 in placental tissues of patients with placenta previa exhibited a significant difference in the cases of scar uterus, history of pelvic inflammation, history of cesarean section, and history of abortion." (PMID 37589008, 2023). "The CXCL12/CXCR4/CXCR7 axis is of great significance in various physiological and pathological conditions, but their functions in placenta previa remain largely unknown." (PMID 37589008, 2023). "CXCL12, CXCR4, and CXCR7 levels in placental tissues were evaluated by IHC, and the findings demonstrated that brownish-yellow staining was seen in the cytoplasm of both syncytiotrophoblasts and cytotrophoblasts in the placental tissues of pregnant women with placenta previa." (PMID 37589008, 2023).
plague (1 paper, 2012). Plague is a severe bacterial infection caused by the gram-negative bacterium Yersinia pestis. "Taken together, these results imply modulation of the CXCR4-SDF-1 axis during pneumonic plague and are consistent with the establishment of a BM—blood gradient of SDF-1, facilitating neutrophil mobilization early after infection." (PMID 23189271, 2012).
plasma cell leukemia (1 paper, 2024). An aggressive plasma cell neoplasm characterized by the presence of neoplastic plasma cells in the peripheral blood. "Importantly, we detected lower expression of CXCR4, which encodes a key molecule for PCs homing to the BM, and integrin gene ITGA6, the downregulation of which was recently connected to progression from MM to plasma cell leukemia." (PMID 38493239, 2024).
plasmacytoma (1 paper, 2020). Plasmacytoma is a localized mass of neoplastic monoclonal plasma cells that represents approximately 5% of all plasma cell neoplasms. "We expected to detect low expression of the adhesion molecule CD56 and the chemokine receptor CXCR4 on plasmacytoma cells." (PMID 32321465, 2020). "We demonstrated a high frequency of CXCR4 expression in plasmacytoma cells." (PMID 32321465, 2020). "Anti-CD56, anti-CD166, anti-CXCR4, anti-Ki-67, and anti-c-MYC antibodies were used for IHC study of plasmacytoma biopsies." (PMID 32321465, 2020).
Pneumocystis infection (1 paper, 2010). "Among the genes that were affected by dexamethasone and further affected by Pneumocystis infection, Mgst1 and Hspa1b genes were down-regulated, while Cd14, Irf8, Il1b, Cxcl13, Cxcr4, Fn1, Irf1, Cd74, S100a9, and Spp1 genes were up-regulated in all four groups." (PMID 20377877, 2010).
polyp (1 paper, 2021). A usually exophytic mass attached to the underlying tissue by a broad base or a thin stalk. "The c-MYC and CXCR4 panel was able to identify polyp/CRC patients with AUC of 0.88 (p < 0.001), with sensitivity and specificity of 84.4% and 92.3%, respectively." (PMID 34335790, 2021). "Here, we demonstrated that c-MYC and CXCR4 dysregulation can be used to detect the existence of polyp and CRC." (PMID 34335790, 2021). "Here, our two-gene panel (c-MYC and CXCR4) showed a decent 80.0% sensitivity for identifying polyp patients, and the performance further increased to 83.3% when future polyp development was included." (PMID 34335790, 2021). "More importantly, c-MYC and CXCR4 were able to identify polyp/CRC patients with AUC values of 0.73 and 0.73, respectively (p < 0.05)." (PMID 34335790, 2021). "We reperformed the ROC analysis for c-MYC, CXCR4, and their combination by including the patients who developed polyp during follow-up in the polyp and CRC groups." (PMID 34335790, 2021). "The expression of both c-MYC and CXCR4 was significantly higher in those who developed polyp." (PMID 34335790, 2021). "This study suggests that the Oct4 and CD26 panel is a promising biomarker for distinguishing CRC from normal and polyp patients, whereas the c-MYC and CXCR4 panel may identify polyp and CRC from normal individuals." (PMID 34335790, 2021). "Our result suggested that the CXCR4 and c-MYC panel may identify both polyp and CRC samples, suggesting their involvement in polyp development and potentially in early carcinogenesis." (PMID 34335790, 2021).
psychological distress (1 paper, 2025). "Overexpression of the C-X-C chemokine receptor type 4 (CXCR4) on CD4+ T cells has been associated with both psychological distress and nutritional status in adolescents with AN, whereas regulatory T cell (Treg) function appears relatively preserved." (PMID 41301477, 2025).
pulmonary atresia (1 paper, 2018). "In summary, while all Cxcl12 and Cxcr4 (not shown) constitutively null embryos had a membranous VSD at E15.5 we found no examples of CAT, IAA-B or retro-oesophageal RSA, nor did we see any examples of pulmonary atresia (part of the tetralogy of Fallot spectrum)." (PMID 30408103, 2018).
relapsing-remitting MS (1 paper, 2022). "which was characterized by secretion of GM-CSF and expression of CXCR4 in relapsing-remitting MS (RRMS)." (PMID 36211343, 2022).
Renal cyst (1 paper, 2020). A fluid filled sac in the kidney. "In renal cyst (RC) cells, the mTOR cascade acts as the downstream of CXCL12/CXCR4 axis, and CXCR4-mediated CXCL2 recognition can selectively active the mTOR signaling to enhance RC cells proliferation." (PMID 32483450, 2020).
reovirus infection (1 paper, 2018). "In the present study, the CXCR4 gene was significantly downregulated in the metabolic pathways of EPC cells after infection with reovirus, indicating that it plays an important role in resistance against reovirus infection." (PMID 29562634, 2018).
Richter syndrome (1 paper, 2021). Transformation of chronic lymphocytic leukemia into aggressive non-Hodgkin's lymphoma, usually diffuse large B-cell lymphoma (immunoblastic or centroblastic variant). "Intriguingly, rare germline mutations in CXCR4 have been found in CLL patients with familial clustering and mutations in regulatory regions of CXCR4 were discovered in biopsies of CLL with aggressive transformation (Richter’s syndrome)." (PMID 34363012, 2021).
salivary gland cancer (1 paper, 2014). A primary or metastatic malignant neoplasm that affects the major or minor salivary glands. "Recently, we also demonstrated that CXCR4 expression contributes to the metastatic potential of salivary gland cancers." (PMID 25536052, 2014).
sciatic nerve lesions (1 paper, 2024). "To investigate potential interactions between CXCR4 signaling and STAT3 in the pro-regeneration state of cervical DRG neurons induced by unilateral sciatic nerve lesions, we administered AMD3100 intrathecally and analyzed the activation and nuclear translocation of STAT3." (PMID 39796050, 2024).
Sensory neuropathy (1 paper, 2014). Peripheral neuropathy affecting the sensory nerves. "Evidence shows that painful HIV sensory neuropathy is influenced by neuroinflammatory events that include the proinflammatory molecules, MAP Kinase, tumor necrosis factor-α (TNFα), stromal cell-derived factor 1-α (SDF1α), and C-X-C chemokine receptor type 4 (CXCR4)." (PMID 25078297, 2014).
sickle cell disease (1 paper, 2012). Sickle cell anemias are chronic hemolytic diseases that may induce three types of acute accidents: severe anemia, severe bacterial infections, and ischemic vasoocclusive accidents (VOA) caused by sickle-shaped red blood cells obstructing small blood vessels and capillaries. "In both subjects with sickle cell disease and the mouse model, fibrocytes expressed a hierarchy of chemokine receptors, with CXCR4 expressed on most fibrocytes, and CCR2 and CCR7 expressed on a smaller subset of cells." (PMID 22442712, 2012).
skin squamous cell carcinoma (1 paper, 2025). A carcinoma arising from the squamous cells of the epidermis. "Moreover, autocrine SDF‐1/CXCR4 signalling induces proliferation and survival, and invasion, promoting in vivo lung metastasis of CSCs for mouse advanced skin squamous cell carcinomas (SCCs)." (PMID 39855896, 2025).
Skin ulcer (1 paper, 2023). A discontinuity of the skin exhibiting complete loss of the epidermis and often portions of the dermis and even subcutaneous fat. "In addition, activation of the SDF-1/CXCR4 signaling pathway and an accumulation of EPCs were observed in skin ulcers sites after TTT surgery." (PMID 37727693, 2023).
soft tissue tumors (1 paper, 2024). "Aware that CXCR4 could be a valuable prognostic factor in cancer and a therapeutic target, it has been hypothesized that CXCR4 expression could be a useful tool to help decision-making in patients with high-risk soft tissue tumors." (PMID 38893721, 2024).
spinal cord injury (1 paper, 2017). Penetrating and non-penetrating injuries to the spinal cord resulting from traumatic external forces (e.g., WOUNDS, GUNSHOT; WHIPLASH INJURIES; etc.). "It was reported that CXCR4 signaling played an important role in the migration and differentiation of endogenous neural stem cells after spinal cord injury (SCI)." (PMID 28246405, 2017).
Streptococcus pneumoniae infection (1 paper, 2025). "Therefore, we finally sought to investigate whether our pharmacologically induced CXCR2 LOF mice also display increased susceptibility to Streptococcus pneumoniae infection and whether CXCR4 antagonism could mitigate this susceptibility." (PMID 41451234, 2025).
synucleinopathy (1 paper, 2022). A neurodegenerative disease that is characterized by the abnormal accumulation of aggregates of alpha-synuclein protein in neurons, nerve fibers or glial cells. "This study also identified discrete populations of α-syn reactive CD4+ T cells that express CXCR4 and IL17A which were present in the cerebro-spinal fluid of synucleinopathy patients and are correlated to the neurodegenerative phenotype." (PMID 35897751, 2022).
systemic mastocytosis (1 paper, 2023). Systemic mastocytosis (SM) comprises a heterogeneous group of rare acquired and chronic hematological malignancies that are related to an abnormal proliferation of mast cells in tissue, including bone marrow, with or without skin involvement. "For instance, the mRNA levels of the receptors CD44 and CXCR4, significantly downregulated in HMC-1.3 compared to HMC-1.2, are important for homing of stem cells, huMCs and/or huMC progenitors and have been associated with hematological malignancies, including systemic mastocytosis." (PMID 37025992, 2023).
T cell deficiency (1 paper, 2022). "In contrast to T cell deficiency, the recurrent tumors were significantly enriched for markers of tumor-associated neutrophils (TANs; eg., CD177, ELANE), tumor-associated macrophages (TAMs; eg., MRC1, CD68), and immune suppressive myeloid cells (MDSCs; eg., ARG1, CXCR4)." (PMID 35919862, 2022).
T-cell neoplasms (1 paper, 2023). "As [18F]FDG has limited sensitivity in the staging of MZL, an additional C-X-C motif chemokine receptor 4 (CXCR4)-directed PET/CT scan using [68Ga]Ga-PentixaFor ([68Ga]Ga-CPCR4.2) was performed, given that CXCR4 is overexpressed by most B- and T-cell neoplasms." (PMID 37099133, 2023).
Thyroid adenoma (1 paper, 2020). The presence of a adenoma of the thyroid gland. "Treating with CXCR4 antagonists significantly inhibits tumor pro-invasive phenotype and knockdown of CCDC80 is susceptible to developed thyroid adenoma and OC." (PMID 32716025, 2020).
tongue cancer (1 paper, 2015). A malignant neoplasm affecting the tongue. "IL-1β induces the up-regulation of CXCR4 in the tongue carcinoma cell line Tca8113, suggesting that CXCR4 is a link between inflammation and cancer." (PMID 26176534, 2015).
transient cerebral ischemia (1 paper, 2021). "Further, Cxcr4 deficiency reduces innate-immune-system-mediated defense response, which is associated with a deteriorating outcome after transient cerebral ischemia." (PMID 34481466, 2021).
urolithiasis (1 paper, 2025). Stone(s) within the urinary tract. "In this study, urinary levels of NPC, HA, and CXCR4 were significantly elevated before stone treatment, implying a potential relationship with crystal formation in urolithiasis patients." (PMID 40275250, 2025).
valvular heart diseases (1 paper, 2018). "Considering the importance of stem cell homing to the cardiomyoplasty outcome, this study analyzed its activation status through the expression of key molecules involved in this mechanism, the chemokine SDF-1 and its receptor CXCR4 in BM samples of patients with ischemic and valvular heart diseases." (PMID 29784000, 2018). "Here, expression the key molecules involved in activation of homing, as the chemokine SDF-1 and its receptor CXCR4 and CXCR7, showed variations once analyzed in BM samples of patients with ischemic and valvular heart diseases." (PMID 29784000, 2018).
viral hepatitis (1 paper, 2012). An acute or chronic inflammation of the liver parenchyma caused by viruses. "CXCR4 and CCR5 are also co-receptors for HIV entry into human cells, but their roles in viral hepatitis have not yet been addressed." (PMID 23158844, 2012).
viral pneumonia (1 paper, 2023). Inflammation of the lung parenchyma that is caused by a viral infection. "In addition, studies have shown that PTP1B inhibitors protect against acute lung injury and regulate CXCR4 signaling in neutrophils, which means that the use of PTB1B inhibitors in patients with severe viral pneumonia may have a preventive effect on ALI/ARDS." (PMID 37359015, 2023).
vulvar carcinoma (1 paper, 2022). "Again, in vulvar carcinoma, CXCR4-targeted imaging could potentially be used to prognosticate patients as well as to select patients who may benefit from therapies targeting CXCR4." (PMID 36140541, 2022).
vulvovaginal candidiasis (1 paper, 2020). Infection of the vulva and vagina with a fungus of the genus CANDIDA. "For instance, miR-1192 could directly reduce inflammation in vulvovaginal candidiasis by restraining the expression of CXCR4." (PMID 32522221, 2020).
wart (1 paper, 2026). "The CXCR4 antagonist plerixafor (AMD3100, Mozobil) durably reverses panleukopenia and in most WHIM patients also induces wart regression; however, its short half-life requires twice daily injection." (PMID 41904735, 2026).